TRIM21 (tripartite motif containing 21)
Diseases named in the same sentence as TRIM21 in open-access papers (continued):
Sharing a sentence is not in itself a finding about the gene and the disease.
hepatocellular carcinoma (30 papers, 2017 to 2025). A malignant tumor that arises from hepatocytes. "In contrast, increased TRIM21 expression in glioma and hepatocellular carcinomas is associated with a poorer prognosis." (PMID 36982215, 2023). "Lower TRIM21 mRNA expression was correlated with reduced patient survival in DLBCLs and in hepatocellular carcinomas; in vitro studies implicated enhanced cell proliferation as a possible cause." (PMID 34552597, 2021). "TRIM21 downregulation has been implicated in unfavourable outcomes for multiple cancer types including breast cancer, hepatocellular carcinoma, diffuse large B-cell lymphomas (DLBCL) and most recently, colitis-associated cancers." (PMID 34552597, 2021). "In hepatocellular carcinoma, stress-induced TRIM21 upregulation mitigates the function of RETREG1 to restore ER stress equilibrium." (PMID 40735642, 2025). "TRIM21 modulates stability of pro-survival, non-coding RNA vtRNA1-1 in human hepatocellular carcinoma cells." (PMID 40565315, 2025). "In the other human hepatoma cell line Huh7, TRIM21 repressed HBV replication, HBeAg, and HBsAg levels similarly to HepG2." (PMID 38780244, 2024). "In this study, we showed the antiviral efficacy of TRIM21 against HBV in hepatoma cell lines, primary human hepatocytes isolated from patient liver tissues, and mouse model." (PMID 38780244, 2024). "In ovarian, renal, and hepatocellular carcinoma, TRIM21 overexpression inhibits cell migration in vitro and in vivo." (PMID 36982215, 2023). "TRIM21 is a tumor-suppressor in hepatocellular carcinoma and it also down-regulates PAR4 (a tumor suppressor) in pancreatic cancer in the presence of cisplatin." (PMID 32228434, 2020). "TRIM21 could also suppress antioxidant response of hepatocellular carcinoma cells by mediating P62 expression." (PMID 40998798, 2025). "In addition, TRIM21 is involved in regulating ACTL6A/MYC axis activity in hepatocellular carcinoma progression." (PMID 37171396, 2023). "In addition, TRIM21 was highly expressed in multiple GI tumors and was associated with poor prognosis in PDAC and hepatocellular carcinoma." (PMID 37587773, 2023). "Of note, TRIM21 expression is downregulated in hepatocellular carcinoma cells and is significantly and inversely correlated with patient prognosis, suggesting that TRIM21 acts as a tumor suppressor by inhibiting hepatocellular carcinoma cell proliferation, migration, and invasion." (PMID 29038421, 2017). "In hepatocellular carcinoma (HCC), ependymin-related protein 1 (EPDR1) plays a regulatory role on PD-L1 expression to mediate immune evasion in a TRIM21-dependent manner." (PMID 40735642, 2025). "Furthermore, TRIM21 level was low in diffuse large B-cell lymphoma and hepatocellular carcinoma and it negatively regulated the development of diffuse large B-cell lymphoma and hepatocellular carcinoma, and its lower expression could predict a shorter 5-year survival and overall survival." (PMID 38720056, 2025). "The HPA database indicated that UBE2O exhibited protein expression patterns opposite those of IFIT3 in both liver tissue and hepatocellular carcinoma tissue, although its expression was positively correlated with that of BST2 and TRIM21." (PMID 38129382, 2023). "The function of TRIM21/Ro52 in colorectal cancer (CRC) and hepatocellular carcinoma (HCC) remains contradictory." (PMID 37993883, 2023). "IFN-γ remarkably increased TRIM21 in PHHs, and unlike in the hepatoma cell lines, TRIM21 levels were also increased by TNF-α." (PMID 38780244, 2024). "We investigated whether the induction of TRIM21 occurs in response to TNF-α and IFN-γ in human hepatoma cell lines and PHHs." (PMID 38780244, 2024). "Moreover, Sorafenib, a standard treatment for hepatocellular carcinoma, increased the sensitivity of TNBC cells to Olaparib by promoting TRIM21-mediated ubiquitination degradation of BRCA1." (PMID 37864041, 2023).
hepatocellular carcinoma (continued). "TRIM21 interacts with HBx protein for ubiquitination degradation, which leads to impaired HBx-mediated degradation of structural maintenance of chromosomes 6 (Smc6) and suppression of HBV replication in hepatoma cell lines." (PMID 36159815, 2022). "However, other ubiquitin ligases, TRIM21 and A20, have been reported to catalyse ubiquitination-mediated degradation of PFKP in glioblastoma and PFKL in hepatocellular carcinoma." (PMID 35670764, 2022). "Here, we describe a regulatory process for vtRNA1-1 stabilization mediated by the newly identified interacting proteins, TRIM21 and TRIM25, in human hepatocellular carcinoma (HCC) cells." (PMID 40096176, 2025). "In hepatocellular carcinoma (HCC), interferon-related developmental regulator 1 (IFRD1) is upregulated by glutamine starvation to inhibit autophagy by promoting TRIM21-mediated degradation ATG14." (PMID 40735642, 2025). "In hepatoma cell lines HepG2 and Huh7, TRIM21 was significantly increased by IFN-γ but not TNF-α." (PMID 38780244, 2024). "TRIM21 inhibits fatty acid (FA) synthesis by ubiquitination and degradation of fatty acid synthase (FASN) in hepatocellular carcinoma, and further studies found that the ubiquitination of FASN by TRIM21 could be inhibited by glyceronephosphate O-acyltransferase (GNPAT)." (PMID 36694250, 2023).
Autoimmunity (24 papers, 2009 to 2026). The occurrence of an immune reaction against the organism's own cells or tissues. "Tripartite motif containing-21 (TRIM21) and interleukin-6 (IL-6) have been implicated in autoimmunity and inflammation, with links to chronic interferon activity." (PMID 41050477, 2025). "Previous studies have indicated that TRIM21 play important roles in inflammation, autoimmunity and cancer." (PMID 37335642, 2023). "This is likely due to isolated anti-Ro52/TRIM21 being associated with a variety of immunological and non-immunological conditions compared to anti-Ro60 and anti-La being more specific for autoimmunity." (PMID 35871174, 2022). "Here, we summarise the structure and function of this enzyme, its roles in innate immunity, adaptive immunity and cellular homeostasis, the pathogenesis of autoimmunity against TRIM21, and the potential impacts of autoantibodies to this intracellular protein." (PMID 34552597, 2021). "Polymorphisms located in regions encoding the LxxIS motif of TRIM21 have not yet been identified and in general, GWAS studies relating to TRIM21 in autoimmunity are limited." (PMID 34552597, 2021). "TRIM21 is an attractive protein for the development of autoimmunity given its role in the cellular innate immune response and surveillance to intracellular pathogens such as viruses." (PMID 32939030, 2020). "Furthermore, TRIM21 overexpression attenuates autoimmunity and related inflammation in MRL/lpr mice, indicating an important regulatory role in the pathogenesis of SLE." (PMID 40610751, 2025). "Indeed, another study similarly found a lower proportion of autoimmunity in patients with isolated anti-Ro52/TRIM21." (PMID 35871174, 2022). "Therefore, TRIM21 may regulate the production of autoantibodies, and dysfunction of TRIM21 could lead to the advancement of autoimmunity." (PMID 39165359, 2024). "In addition, TRIM21 is involved in cancer, inflammation, intracellular immunity, and autoimmunity." (PMID 31540324, 2019). "The isolated anti-Ro52/TRIM21 group tended to be older compared to the anti-Ro52/TRIM21 combined with anti-Ro60 and/or -La, so it is surprising that additional time did not manifest in proportionally more clinical autoimmunity." (PMID 35871174, 2022).
glioma (22 papers, 2021 to 2025). A benign or malignant brain and spinal cord tumor that arises from glial cells (astrocytes, oligodendrocytes, ependymal cells). "To further explore the correlation between TRIM21 expression and pathological characteristics, we evaluated the association of TRIM21 with glioma classification and found its mRNA was positively related with glioma grade." (PMID 37771771, 2023). "In our research, up-regulated in IDH1-WT gliomas, TRIM21 was associated with advanced tumor grade and poor prognosis." (PMID 37771771, 2023). "Elevated TRIM21 levels were significantly associated with a poor prognosis in all glioma types, including HGGs and GBM, suggesting an oncogenic role for this TRIM protein." (PMID 36139694, 2022). "Gain-of-function or loss-of-function assays in glioma cell lines indicated that TRIM21 mediates cell proliferation and migration." (PMID 36139694, 2022). "Higher levels of TRIM21 expression are associated with a poor prognosis of glioma and promote proliferation, drug resistance, and migration of glioma cells." (PMID 36118697, 2022). "To this end, we identified TIF1γ, another glioma associated tumor suppressor and E3 ligase for β-catenin 14, regulates the inactivation of Wnt/β-catenin cascade, our data support that TIF1γ may act as a substrate in the TRIM21-mediated response." (PMID 37771771, 2023). "Conversely, TRIM21/Ro52 enhances the proliferation and migration of cancer cells in glioma and thyroid cancer, while also contributing to increased drug resistance in colorectal and pancreatic cancers." (PMID 40429494, 2025). "In glioblastoma, a tissue microarray analysis of glioma samples revealed an inverse relationship between TRIM21 and TIF1γ expression levels, while TRIM21 was positively correlated with β-catenin levels." (PMID 40723303, 2025). "Multivariate analyses revealed that TRIM21 was an independent indicator for overall survival of patients with glioma." (PMID 40735642, 2025). "To evaluate the clinical importance of the TRIM21/TIF1γ/β-catenin axis and determine their correlation in glioma, we analyzed 120 human glioma specimens with using IHC staining." (PMID 37771771, 2023). "This, is demonstrated in our report, the mRNA and protein expression of TRIM21 was much higher in gliomas." (PMID 37367937, 2023). "Endogenous TRIM21 levels are found to be inversely correlated with TIF1γ but positively correlated with β-catenin in glioma tissue microarray experiments." (PMID 37771771, 2023). "In contrast, TRIM21/Ro52 promotes cancer cell proliferation and migration in glioma and thyroid cancer, and it increases drug resistance in colorectal and pancreatic cancers." (PMID 37993883, 2023). "Research demonstrates that by regulating cell proliferation, migration, and senescence, TRIM21 overexpression promotes glioma progression." (PMID 37367937, 2023). "Experiments in xenograft murine models confirmed the oncogenic potential of TRIM21 since mice injected with glioma cells overexpressing TRIM21 or depleted of TRIM21, exhibited decreased and increased OS, respectively, compared to control mice." (PMID 36139694, 2022). "We found that TRIM21 expression levels are potentially elevated in a wide spectrum of tumors, including glioma, melanoma, pancreatic adenocarcinoma, testicular germ cell tumors, acute myeloid leukemia, cholangio carcinoma and colorectum adenocarcinoma." (PMID 35048968, 2022). "According to the combined analysis of TCGA and GTEx data, TRIM21 is upregulated in a wide spectrum of cancers, such as glioma, melanoma, pancreatic adenocarcinoma and colorectum adenocarcinoma." (PMID 35048968, 2022).
glioma (continued). "Glial cell line-derived neurotrophic factor (GDNF) promotes glioma development and progression, and TRIM21-mediated cAMP response element-binding protein (CREB) ubiquitination decreases the transcription of GDNF and inhibits glioma genesis and development." (PMID 36159815, 2022). "Among them, POLR2F, DYNC1H1, and SMAD9 in tumor tissues of patients with glioma were downregulated as compared to normal tissues adjacent to cancer, while TRIM21, BRCA1, and ERI1 were upregulated." (PMID 36118697, 2022). "Therefore, targeting TRIM21 is a promising therapeutic strategy for glioma with hyperactive β-catenin." (PMID 40735642, 2025). "In 120 glioma samples, high TRIM21 protein level was correlated with advanced tumor stage." (PMID 40735642, 2025). "TRIM21 is a promising therapeutic and prognostic biomarker for glioma with hyperactive β-catenin." (PMID 37771771, 2023). "Importantly, our data also indicate that the TRIM21/TIF1γ/β-catenin axis plays a critical role in the clinical behavior of human glioma." (PMID 37771771, 2023). "Therefore in vivo treatment with TRIM21 siRNA reduced tumor sizes, indicating TRIM21 as a therapeutic target for glioma." (PMID 37771771, 2023). "Taken together, abundance TRIM21 may contribute to progression of glioma in cancer-affected individuals." (PMID 37771771, 2023). "Moreover, he increased expression of TRIM21 was significant, positively correlated with the highest tumor grade and diverse subtypes in gliomas." (PMID 37367937, 2023). "Furthermore, IDH1 mutation was an important classification biomarker for glioma 29, The IHC results showed that compared with the IDH1-MT, the expression levels of TRIM21 and β-catenin are significantly upregulated but TIF1γ decreased in IDH1-WT glioma." (PMID 37771771, 2023). "TRIM21 has been recently shown to serve as a poor prognosis marker in gliomas." (PMID 36139694, 2022). "In addition, differential expression analysis between control and TRIM21-silenced glioma cells revealed numerous genes involved in cellular senescence pathways." (PMID 36139694, 2022). "In vitro work suggests that TRIM21 promotes glioma cell resistance to TMZ." (PMID 36139694, 2022). "In literature, only BRCA1, TRIM21, and POLR2F have been implicated in the progression of glioma." (PMID 36118697, 2022). "Thus, our data indicate that TRIM21 in combination with β-catenin could serve as a valuable prognostic biomarker set for glioma patients." (PMID 37771771, 2023). "Therefore, TRIM21-mediated TMZ resistance could justify the poor prognosis of glioma patients with a high TRIM21 expression." (PMID 36139694, 2022). "TRIM21-mediated degradation of interferon gamma inducible protein 16 (IFI16) and hu-antigen R (HuR) inhibits radiation therapy resistance in stemness of gliomas." (PMID 39154024, 2024). "Of the TRIM proteins, TRIM21 is identified as a prognostic biomarker and a regulator of malignancy for GBM using public databases and clinical glioma specimens." (PMID 37771771, 2023). "Lin established a 6-RBP gene signature consisting of POLR2F, DYNC1H1, SMAD9, TRIM21, BRCA1, and ERI1 in another bioinformatics work, allowing for a complete assessment of glioma and ischemic stroke." (PMID 37884559, 2023). "Consistent with the role as an oncogene, TRIM21 overexpression, was also significantly correlated with poor OS, DSS, PFI in all of the patients with glioma." (PMID 37367937, 2023).
glioma (continued). "The volcanic plot showed the differential analysis results of these six RBP genes, which showed that POLR2F and DYNC1H1 were downregulated in glioma, while TRIM21, BRCA1, ERI1, and SMAD9 were upregulated in glioma." (PMID 36118697, 2022). "TRIM24, TRIM47, TRIM44, TRIM31, TRIM14, TRIM21, and TRIM28 have exhibited significant prognostic value regarding OS and/or PFS of glioma patients." (PMID 36139694, 2022). "First, six prognostic-related RBP genes (POLR2F, DYNC1H1, SMAD9, TRIM21, BRCA1, and ERI1) were obtained from the TCGA-glioma dataset." (PMID 36118697, 2022). "In all WHO grade II-IV gliomas, DNAss was positively correlated with the RBPS score, ERI1, BRCA1, and TRIM21, while negatively correlated with POLR2F, DYNC1H1, and SMAD9 [Spearman correlation, Benjamini-Hochberg (BH)-adjusted p < 0.05]." (PMID 36118697, 2022). "Additionally, high TRIM21 expression predicted significantly reduced overall survival (OS) and disease-free survival (DFS) rates in patients with glioma." (PMID 37771771, 2023).